CDK6 (cyclin dependent kinase 6)
Diseases named in the same sentence as CDK6 in open-access papers (continued):
Sharing a sentence is not in itself a finding about the gene and the disease.
liver cancer (13 papers, 2016 to 2024). An epithelial or non-epithelial malignant neoplasm that arises from the liver. "Functional analyses show that CDK6 is crucial in regulation of acquired lenvatinib resistance in HCC via augmentation of liver cancer stem cells with clinical significance." (PMID 37872167, 2023). "Possible therapies for the overexpressed kinases include CDK4/CDK6 inhibitors, such as Palbociclib, which has been shown effective in human liver cancer cell lines and mouse models with intact tumor suppressor Retinoblastoma (Rb1)." (PMID 35433463, 2022). "On the other hand, overexpression of cyclin-dependent kinases (CDK6 and Cyclin D1) was observed in untreated breast, lung, and liver cancer cells in the present study, corroborating previous reports." (PMID 31783627, 2019). "In liver cancer tissues, the expressions of CDK4 (p = 1E-12) and CDK6 (p = 5.74E-14) were significantly increased." (PMID 34335258, 2021). "H2A.Z.1 depletion selectively suppressed positive G1/S cell cycle components, such as CDK4, CDK6, cyclinD1 and CDK2, and simultaneously induced the expression of potent negative cell cycle regulators, p21WAF1/Cip1 and p27Kip1, in liver cancer cells." (PMID 26863632, 2016). "Interestingly, previous in vitro investigation reported a cell cycle arrest in the G1 phase in liver cancer cells treated with ponatinib, and identified that this cell cycle blockade was mediated by a reduction in the function of the CDK4/CDK6/Cyclin D1 complex." (PMID 32719607, 2020). "Interestingly, a study in liver cancer model showed that tumor cells that failed at H3K9Ac/H3K9Me3 transition, could lead to the hyperacetylation of H3K9 and increased expression of many oncogenes such as Kras, Ercc1, Cdk6, Usp39, and Mapre352." (PMID 36064736, 2022). "The E2F1 gene was moderately expressed in normal liver tissue and highly expressed in liver cancer tissue; The CDKN1A and CDK6 were not expressed in liver cancer tissues or normal liver tissues." (PMID 36699068, 2022).
breast tumor (11 papers, 2006 to 2025). "In PubMed, The most frequently occurring words were human, cyclin-dependent kinase 4, female, animals, cyclin-dependent kinase 6, breast neoplasms, cell line, drug resistance, protein kinase inhibitors, and mice." (PMID 36530984, 2022). "To further explore the clinical relevance of CDK6 expression, we performed immunohistochemistry (IHC) analysis of a tissue microarray featuring of 343 cases of breast tumor samples that contains 56 cases of recurrence disease from Kentucky." (PMID 30518851, 2018). "Analysis of The Cancer Genome Atlas's (TCGA) ER+ breast tumour cohort revealed alterations in the CDK4/CDK6/cyclin D pathway in about 35% of the patients, making them an ideal population for targeting CDK4 and CDK6." (PMID 28653662, 2017). "Overexpression of cdk6 in breast tumor cells in culture has been shown to suppress proliferation, unlike the growth stimulating effects of its close homolog, cdk4." (PMID 24848372, 2014). "Cdk6 protein levels were reduced in most breast tumor clinical samples examined, especially in the cell nuclei, as compared to cells in normal breast tissue, regardless of tumor cell morphology." (PMID 24848372, 2014). "Many breast tumor cell lines have low or undetectable levels of cdk6 and overexpression of cdk6 by transfection reduces their rate of growth." (PMID 24848372, 2014). "Ectopic expression of parkin in breast tumor cells also decreased their proliferation rate, with a concomitant increase in cdk6 levels." (PMID 24848372, 2014). "However, the CDK4/6 inhibitor Palbociclib, similar to that of BET inhibitor, achieved a synergistic effect with AKTi in suppressing breast tumor cell growth, suggesting that the kinase activity of CDK6 is important for the intrinsic resistance to AKTi." (PMID 30518851, 2018). "In addition to directly affecting proliferation, alterations in cdk6 or cdk4 levels in breast tumor cells also differentially influence levels of numerous steroid metabolic enzymes (SMEs), including those involved in estrogen metabolism." (PMID 24848372, 2014). "For example, increased cyclin D1 and decreased cdk6 levels are seen in many human breast tumors." (PMID 24848372, 2014). "Abrogation of Rb pathway function is frequent in breast tumors by loss of expression of Rb or altered expression of inhibitors of Rb activity (e.g. loss/silencing of CDKN2A (p16) and amplification and/or over expression of CCND1, CDK4, CDK6)." (PMID 16620391, 2006). "For the treatment of breast tumors that include hormone receptors, CDK4 and CDK6 inhibitors have been authorized." (PMID 38231074, 2025). "In breast tumor cells, ICAM1 promotes many pathways and signature genes related to stemness and the cell cycle, including CDK6 as one of the essential targets." (PMID 34381029, 2021). "In consistent with the fact that circPGR regulates the expression of CDK1, CDK6 and CHEK2, the expression of these genes was significantly higher in ER-positive breast tumor tissues compared to that of adjacent normal tissues." (PMID 33408778, 2021). "Evidence has shown that normal human mammary epithelial cells (HMECs) exhibit a high level of CDK6 activity, but all breast tumor-derived cell lines exhibit lower CDK6 activity levels, with several having little or no CDK6 activity." (PMID 25739977, 2015).
endometrial cancer (11 papers, 2000 to 2025). Primary or metastatic malignant neoplasm involving the endometrium (mucous membrane that lines the endometrial cavity). "PI3K inhibitors have been found to inhibit the proliferation of endometrial cancer cells by decreasing CDK6, increasing p27 and subsequently inducing G1 phase arrest." (PMID 38424516, 2024). "We found that PQR309, a dual PI3K/mTOR inhibitor, reduces proliferation in endometrial cancer cells and endometrial cancer stem cells by decreasing CDK6 and increasing p27 and subsequently inducing G1-phase arrest." (PMID 34831139, 2021). "Among them, NCT03643510, in which cancer response is evaluated in a prospective, single arm phase II study of the combination of CDK4 and CDK6 dual inhibitor abemaciclib and selective estrogen receptor degrader fulvestrant in hormone receptor positive recurrent endometrial carcinomas." (PMID 35629078, 2022). "PQR309 decreased the protein expression of CDK6 in endometrial cancer cells." (PMID 34831139, 2021). "We analysed p16 gene alteration and p16, cyclin-dependent kinase 4 (CDK4), CDK6, cyclin D1, cyclin D2, cyclin D3 and retinoblastoma protein (pRb) expression in ten normal endometriums (PE), 18 endometrial hyperplasias (EH) and 35 endometrial cancers (EC)." (PMID 10682682, 2000).
neutropenia (11 papers, 2018 to 2025). A decrease in the number of neutrophils found in the blood. "On the other hand, CDK6 is the primary kinase in bone marrow progenitors, and inhibiting CDK6 is thought to cause neutropenia." (PMID 38339303, 2024). "It is likely that abemaciclib’s superior affinity for CDK4 over CDK6 led to its possible dose-limiting toxicity of diarrhea, whereas palbociclib and ribociclib are associated with neutropenia." (PMID 37366898, 2023). "A higher activity of abemaciclib against CDK4 than against CDK6 has been suggested as the reason for reduced neutropenia compared with other CDK4/6 inhibitors." (PMID 30443290, 2018). "Our results demonstrate that apigenin and specific flavonoids form a potent bond with the CDK6 protein (but less potent than ribociclib, a CDK6 inhibitor), presenting a potential benefit when combined with ribociclib to reduce neutropenia and gastrointestinal toxicity induced by ribociclib." (PMID 40141193, 2025). "The higher and more selective activity of abemaciclib against CDK4 than CDK6, as well as the ratio of unbound Cmax to CDK6 potency, may explain the different rates of neutropenia observed among treatments." (PMID 35813283, 2022). "Consistent with the safety profile of other CDK4/6 inhibitors with similar potencies for CDK4 and CDK6 (palbociclib and ribociclib), the most frequent grade 3 or 4 AEs of dalpiciclib were neutropenia and leukopenia, observed in 52.5 and 35.0% of patients respectively." (PMID 33845905, 2021). "Alternatively, the lower selectivity of abemaciclib could lead to off-target dose-limiting toxicities due to diarrhea before sufficient CDK6 inhibition can be achieved, which would subsequently lead to neutropenia." (PMID 30443290, 2018). "We investigated how CDK6 inhibition with indole-3-carbinol (I3C) or systemic Cdk6-deficiency in a murine model of arthritis ameliorates the progression of pathological changes and suppresses synovial hyperplasia without affecting myelosuppression, particularly neutropenia." (PMID 39940918, 2025). "PF-07220060 does not inhibit CDK6, which is the main mediator of neutropenia, and this may allow higher doses in a continuous fashion that could result in better patient outcomes." (PMID 37921419, 2023).
brain tumor (10 papers, 2012 to 2025). "Meanwhile, CDK4 and CDK6 were identified as the target of miR-124 and sensitizes brain tumor to radiotherapy." (PMID 39865088, 2025). "Besides PRUNE_1, the other five genes (i.e., KIF11, KIF14, ASPM, CDK6, and ATR) have been reported as mutated in hereditary MCPH and overexpressed in primary brain tumors (e.g., MB)." (PMID 34745995, 2021). "Similarly, miR-124 and miR-137 inhibit proliferation of GBM cells and induce differentiation of brain tumor stem cells by inhibiting CDK6." (PMID 23594394, 2013). "It has been reported that miR-137 induces differentiation of brain tumor stem cells and inhibits proliferation of GBM cells by post-transcriptional repression of cyclin-dependent kinase 6 (CDK6)." (PMID 35965517, 2022).
oral cancer (10 papers, 2014 to 2024). "For instance, circRNA-100290 co-expressed with CDK6 as a miR-29 sponge and contributed to the tumorigenesis of oral cancer." (PMID 36672755, 2022). "Recent results indicate that in oral carcinoma cells miR-149-5p targets CDK6, an oncogene that regulates the cell cycle." (PMID 34439138, 2021). "Some evidence has suggested that miR-145 may function as a primary, direct tumor suppressor in other cancers and may function similarly to inhibit c-myc and CDK6 in oral cancers." (PMID 38396844, 2024). "After observing the inhibitory effect of AGA extracts on the viability and colony formation ability of oral cancer cells, we further evaluated by the expression levels of cell cycle regulators (CDK4, CDK6, cyclin A, B1, D1 and E2) by qPCR and Western blot." (PMID 33142749, 2020). "Additionally, capsaicin-induced a G0/G1 phase arrest in oral cancer cells through the reduction of cyclin-D (CCND), cyclin-dependent kinase 2 (CDK2), and cyclin-dependent kinase 6 (CDK6), and an increase in the levels of p21 and p16." (PMID 35600864, 2022). "Furthermore, as the progression of the cell cycle is regulated by a complex of cellular cyclins and cyclin-dependent kinases (CDKs), our results suggest that the anti-proliferative effects of AGA in oral cancer cells may be through inhibiting CDK4 and CDK6." (PMID 33142749, 2020).
sarcoma (10 papers, 2019 to 2024). A usually aggressive malignant neoplasm of the soft tissue or bone. "The overall survival rate was negatively correlated with CDK6 expression in both lung caner and sarcoma." (PMID 37833461, 2023). "Notable among the twenty five top genes found to be co-expressed with ctag1b/a in sarcomas are protocadherin β3, tumor necrosis factor alpha-induced protein 8-like 3, demethylase jumonji domain containing 2C, cyclin-dependent kinase 6, and glycine dehydrogenase (decarboxylating)." (PMID 35664317, 2022). "The availability of CDK4 and CDK6 cyclin inhibitor drugs (anti-CDK4 and anti-CDK6) makes them excellent choices for targeting sarcomas with these genetic alterations in the form of deletions or amplifications." (PMID 38275873, 2024). "Molecular analyses of pediatric and AYA sarcomas have led to the identification of cyclin-dependent kinases (CDK) CDK4 and CDK6 as a therapeutic targeting opportunity." (PMID 35892870, 2022). "In other sarcomas with entirely different histologies, such as epithelioid hemangioendothelioma or high-grade chondrosarcomas, genetic alterations affecting CDK4 and CDK6 have also been described." (PMID 38275873, 2024). "In such cases, this potential indication could be extended to any type of sarcoma, with alterations in the regulation of CDK4 and CDK6." (PMID 38275873, 2024). "Functional diversity of CDK4 and CDK6 have not been investigated in sarcomas and warrants further investigation." (PMID 36612255, 2022). "It is currently not known if CDK4 and CDK6 differential regulation is operative in sarcomas, and it is an area that is worthy of investigation." (PMID 35892870, 2022).
mantle cell lymphoma (9 papers, 2012 to 2021). Mantle cell lymphoma is a rare form of malignant non-Hodgkin lymphoma affecting B lymphocytes in the lymph nodes in a region called the ``mantle zone''. "Levels of CDK6, a verified target of miR-29 in mantle cell lymphoma, remained unchanged, indicating cell type specific downregulation of targets by miR-29 family members." (PMID 28611288, 2017). "Early phase I and phase II studies suggest that this drug is well tolerated and demonstrates efficacy in cancers that are driven by CDK4 and CDK6 such as mantle cell lymphoma." (PMID 24098593, 2013). "In mantle cell lymphoma, miR-29 was shown to regulate cyclin-dependent kinase 6 (CDK6) mRNA to influence cell division; down-regulation of miR-29 was correlated with increased CDK6 and decreased survival." (PMID 23335942, 2012). "Besides CDK4 and CDK6, ON123300 and ON108110 inhibit PI3Kδ and CK2, respectively, and induced Rb dephosphorylation, G1 arrest, and apoptosis in mantle cell lymphoma." (PMID 34065376, 2021).
oral squamous cell carcinoma (9 papers, 2013 to 2025). "Overexpression of circRNA_100290 upregulated CDK6 expression by relieving the miR-29-family-mediated inhibition of CDK6, and this ultimately led to sustaining the cell cycle and proliferation of oral squamous cell carcinomas." (PMID 30187887, 2018). "Recently, up-regulated circRNA_100290 was discovered co-expressed with CDK6 by sponging miR-29b in oral squamous cell carcinomas tissue." (PMID 30068360, 2018). "Similarly, it was reported that Yap1 formed complex with TEAD4 in the nuclei regulating the transcriptions of G1 arrest-related genes, such as CCND1, CCNE, CDK2, CDK4, and CDK6, in human oral squamous cell carcinomas." (PMID 31455378, 2019). "Moreover, in oral squamous cell carcinomas, circRNA_100290 regulate CDK6 expression through sponging miR-29b family members." (PMID 29156822, 2017).
clear cell renal cell carcinoma (8 papers, 2015 to 2025). "MiR-4429 suppresses cell proliferation, migration, invasion, and EMT via modulating CDK6 in clear cell renal cell carcinoma." (PMID 32469064, 2020). "CDK4 and CDK6 expression are decreased by miR-1 and contribute to inhibition of cell cycle progression and metastasis in clear cell renal cell carcinoma." (PMID 27818681, 2016). "Collectively, these data suggest that miR-1 directly suppresses CDK4, CDK6, Caprin1 and Slug expression in clear cell renal cell carcinoma." (PMID 26036633, 2015). "Similarly, Pan et al23 discovered that miR‐4429 inhibits cell proliferation, migration, invasion, and epithelial‐mesenchymal transition (EMT) by targeting CDK6 in clear cell renal cell carcinoma and its expression status is closely related to lymph node metastasis." (PMID 34152098, 2021). "In renal cell clear cell carcinoma, the miR-1 targeted and regulated cell cycle proteins such as CDK4, CDK6, Caprin1 and Slug." (PMID 26807210, 2015).
nasopharyngeal carcinoma (8 papers, 2014 to 2025). A carcinoma arising from the nasopharyngeal epithelium. "At the same time, the overexpression of CDK4 is a poor prognostic factor of nasopharyngeal carcinoma (NPC) and influences tumor progression by regulating the p21/CCND1/CDK6/E2F1 signaling pathway." (PMID 36292719, 2022). "In previous studies, miR-26a/b have been shown to block the G1/S transition of the cell cycle by targeting CCND2, CCNE1/2, CDK6, and EZH2 in HCC and nasopharyngeal carcinoma, and to restrain metastasis by suppressing the expression of IL6 in HCC." (PMID 24565101, 2014). "Western blot results showed that nasopharyngeal carcinoma CNE-2Z cells expressed CDK4 and CDK6." (PMID 27451945, 2016). "Previous studies have revealed that CDK6 enhances radioresistance in human malignancies including nasopharyngeal cancer and HPV negative head and neck squamous cell carcinoma possibly by promoting RAD51 and BRCA1 expression and thereby activating homologous recombinational (HR) DNA repair after IR." (PMID 34395263, 2021).
T-cell acute lymphoblastic leukemia (8 papers, 2013 to 2025). Acute lymphoblastic leukemia of T-cell origin. "mTOR inhibition and subsequent miR21 upregulation was shown to repress Cdk6 in T cell acute leukemia, resulting in decreased tumor proliferation." (PMID 35572197, 2022).
anemia (7 papers, 2017 to 2025). A reduction in the number of red blood cells, the amount of hemoglobin, and/or the volume of packed red blood cells. "Simultaneous knockout of CDK4 and CDK6, although causing embryonic mouse death, is considered to be a result of erythrocyte defects caused by CDK6 deficiency, leading to severe anemia." (PMID 37686364, 2023). "Embryos of Cdk6 or Cdk4 knock out mice died at the late stage of embryonic development because of the hematopoietic-deficiency caused anemia." (PMID 32047552, 2020). "In contrast, embryos defective for Cdk4 and Cdk6 die during the late stages of embryonic development because of severe anemia." (PMID 31430272, 2019). "Experiments with gene-deficient mice for CDK4 or CDK6 are viable, then lacking CDK4 and CDK6 die of severe anemia and hematopoietic abnormalities." (PMID 28193906, 2017). "A lack of CDK6 usually leads to anemia, while overexpression leads to hematologic malignancies." (PMID 32153632, 2020).
endometriosis (7 papers, 2020 to 2025). The growth of functional endometrial tissue in anatomic sites outside the uterine body. "This agrees with previous studies in which CDK6 was reported to be significantly upregulated in the eutopic endometrium of endometriosis patients compared to healthy endometrium." (PMID 40135061, 2025). "We have found a significant upregulation of CDK6 in deep endometriosis lesions and ovarian endometriosis lesions compared to healthy endometrium tissue." (PMID 40135061, 2025). "AC002454.1 is upregulated with cyclin-dependent kinase-6 (CDK6) in patients with endometriosis, and there was a significant positive correlation between them." (PMID 35103065, 2022). "In particular, it was proposed that AC002454.1 controls CDK6, a cell cycle regulator, which may impact the pathophysiology of endometriosis." (PMID 40757146, 2025). "Moreover, CDK6 was shown to be significantly upregulated in eutopic and ectopic endometriosis patients compared to their healthy control." (PMID 40135061, 2025). "The biological behavior of endometrial cells may be cooperatively influenced by AC002454.1 and CDK6, which may work in concert to encourage the growth of endometriosis." (PMID 37455911, 2023). "CDK6 was found to upregulate the expression of lncRNA AC002454.1 and further accelerate cell cycle, which promoted the progression of endometriosis." (PMID 32112646, 2020). "Moreover, a significant downregulation of several potential targets, including CDK6, BCCIP, PTEN, TCF7L1, TCF7L2, ROBO1, COL4A2, E‐Cadherin, and N‐Cadherin, was observed in the transfected cells and endometriosis patients." (PMID 40135061, 2025).